UGP2 (UDP-glucose pyrophosphorylase 2)
Description:
UTP--glucose-1-phosphate uridylyltransferase catalyzing the conversion of glucose-1-phosphate into UDP-glucose, a crucial precursor for the production of glycogen.
Synonyms: UDPGP; UGP1; UGPP1; SVUGP2; DEE83; EIEE83; UDPG; UDPGP2; UGPP2; pHC379
Tractability: Small molecule: a structure with a bound ligand is known. PROTAC: ubiquitination databases record sites on it; its protein half-life has been measured.
Target class: Enzyme; Transferase
Gene: Protein-coding gene on chromosome 2 (63,840,950 to 63,891,590, forward strand). Ensembl gene ENSG00000169764.
Subcellular location: Cytoplasm
Subcellular location (Human Protein Atlas): Centrosome; Mitochondria; Nucleoplasm
Pathways (Reactome):
Metabolism: Formation of the active cofactor, UDP-glucuronate; Glycogen synthesis
Gene Ontology:
Molecular function: identical protein binding; protein binding; UTP:glucose-1-phosphate uridylyltransferase activity; uridylyltransferase activity; UTP-monosaccharide-1-phosphate uridylyltransferase activity
Biological process: brain development; glycogen biosynthetic process; UDP-alpha-D-glucose metabolic process; glycogen metabolic process
Cellular component: cytoplasm; extracellular exosome; nucleus; cytosol
Genetic constraint (gnomAD): Loss-of-function variants: 34 observed, 45.67 expected, observed/expected ratio (o/e) 0.74, 90% interval 0.56 to 0.99. The upper end of that interval is the gene's LOEUF score, 0.99, which puts it in group 4 of 6, group 1 being the genes least tolerant of losing a copy. Missense variants: 435 observed, 589.57 expected, observed/expected ratio (o/e) 0.74, 90% interval 0.68 to 0.8. Synonymous variants: 208 observed, 210.53 expected, observed/expected ratio (o/e) 0.99, 90% interval 0.88 to 1.11.
Homologues: Orthologues: macaque UGP2 (99% identical), guinea pig UGP2 (99% identical), pig UGP2 (99% identical), rat Ugp2 (99% identical), chimpanzee UGP2 (99% identical), mouse Ugp2 (99% identical), tropical clawed frog ugp2 (89% identical), zebrafish ugp2b (83% identical), zebrafish ugp2a (82% identical), Caenorhabditis elegans rml-1 (65% identical), Drosophila melanogaster UGP (62% identical). Paralogues in human: UAP1 (20% identical), UAP1L1 (20% identical).
Diseases named in the same sentence as UGP2 in open-access papers:
UGP2 is named in the same sentence as 40 diseases in open-access papers, as found by Europe PMC text mining. Sharing a sentence is not in itself a finding about the gene and the disease. The quoted sentences say what the papers report.
hepatocellular carcinoma (8 papers, 2015 to 2025). A malignant tumor that arises from hepatocytes. "For instance, UGP2 expression is downregulated in hepatocellular carcinoma (HCC), where it is significantly associated with fatty acid metabolism, and its downregulation predicts poor prognosis in patients with HCC." (PMID 41614807, 2025). "It has been pointed out that UGP2, a key enzyme in glycogen biosynthesis, has been demonstrated to be related to the occurrence and development of a variety of cancers, including hepatocellular carcinoma (HCC)." (PMID 34621168, 2021).
liver cancer (4 papers, 2017 to 2025). An epithelial or non-epithelial malignant neoplasm that arises from the liver. "UGP2 exhibits a consistently reduced expression in various cohorts of liver cancer patients, and the lower levels emerge as a significant prognostic factor in these cohorts." (PMID 38990489, 2025). "In liver cancer cells, overexpression of UGP2 can promote cell migration and invasion while enhancing extracellular glycogen production." (PMID 38539937, 2024).
colorectal cancer (3 papers, 2020 to 2025). A primary or metastatic malignant neoplasm that affects the colon or rectum. "Previously, several studies have reported the relationship between UGP2 and the occurrence and development of several tumours, including pancreatic ductal carcinoma, gallbladder cancer, colorectal cancer, acute myeloid leukaemia, and glioma." (PMID 32733617, 2020). "Previous studies have reported abnormal expression levels of UGP2 in various cancer types, including pancreatic ductal carcinoma, gallbladder cancer, colorectal cancer, acute myeloid leukaemia, glioma, and HCC." (PMID 32733617, 2020).
pancreatic cancer (3 papers, 2018 to 2022). "It has been shown that UGP2 is associated with pancreatic cancer, glioma, and other malignancies." (PMID 35937991, 2022). "Positive expression of UGP2 and CFL1 can serve a valuable prognostic factor in pancreatic cancer." (PMID 29347944, 2018). "No study on the UGP2 expression level in other epithelial malignancies, including pancreatic cancer, has been reported in the literature." (PMID 29347944, 2018).
pancreatic ductal carcinoma (3 papers, 2018 to 2023). "UGP2 has been recognized as a crucial factor in cancer maintenance and has emerged as a potential therapeutic target in pancreatic ductal adenocarcinoma (PDAC)." (PMID 37760606, 2023). "Positive UGP2 and CFL1 expression was negatively correlated with the postoperative survival time and positively correlated with the mortality of the patients with pancreatic ductal carcinoma." (PMID 29347944, 2018). "The results of this study showed that the positive expression rates of the UGP2 and CFL1 proteins were significantly higher in pancreatic ductal carcinoma than those in paracancerous tissues and benign lesions (P < 0.05 or P < 0.01)." (PMID 29347944, 2018). "UGP2 and CFL1 were positively expressed in 62 (58.5%) and 56 (52.8%) of the 106 pancreatic ductal carcinoma cases, respectively." (PMID 29347944, 2018). "The UGP2 and CFL1 expression levels were positively correlated in pancreatic ductal carcinoma (P = 0.006)." (PMID 29347944, 2018). "Furthermore, the relationship of the expression levels of UGP2 and CFL1 to the prognosis of patients with pancreatic ductal carcinoma was explored." (PMID 29347944, 2018). "This study investigated UGP2 (uridine diphosphate-glucose pyrophosphorylase-2) and CFL1 (cofilin-1) expression in pancreatic ductal carcinoma (PDC), paracancerous tissue (PT), benign lesions (BL), and normal tissue (NT) and their clinicopathological significance." (PMID 29347944, 2018).
breast carcinoma (2 papers, 2019 to 2021). "Although not studied in the context of breast cancer, UGP2 expression (both high and low) has been implicated in the progression of other cancers, and our data suggest a potential uncharacterized role for UGP2 in breast cancer in the context of treatment." (PMID 33932086, 2021). "Of interest for future study are top sensitivity hit UGP2 and resistance hit COPS4 which were the most lowly expressed and highly expressed screen hits in the large chemotherapy treatment‐resistant breast cancer patient tumor cohort." (PMID 33932086, 2021).
developmental epileptic encephalopathy (2 papers, 2020). "Further, after the completion of the work presented here, UGP2-deficient patients presenting with developmental epileptic encephalopathy (DEE) have been described." (PMID 32188137, 2020). "Recently, after the completion of this work, UGP2 mutations in the human population were reported to underlie some forms of developmental epileptic encephalopathy (DEE)." (PMID 32188137, 2020).
gallbladder cancer (2 papers, 2020 to 2021). "In humans, the loss of function of UGP2 caused a genetic disease, and the UGP2 expression was correlated with clinicopathological and biological behaviors, which could be used as a biomarker for progression and poor prognosis of gallbladder cancer." (PMID 34177996, 2021). "Similarly, UGP2 is also a potential biomarker for the progression and prognosis of gallbladder cancer and human glioma." (PMID 32733617, 2020).
cardiomyopathy (1 paper, 2025). A disease of the heart muscle or myocardium proper. "Additionally, a disease–gene association circos plot generated using RAW Graphs 2.0 showed tight linkage of hub DEGs such as DAPK2, DUSP3, IL6R, and UGP2 to cardiovascular comorbidities, including heart failure, diabetic retinopathy, cardiomyopathy, and pulmonary hypertension." (PMID 41262879, 2025).
endothelial dysfunction (1 paper, 2025). In vascular diseases, endothelial dysfunction is a systemic pathological state of the endothelium (the inner lining of blood vessels) and can be broadly defined as an imbalance between vasodilating and vasoconstricting substances produced by (or acting on) the endothelium. "These included genes such as CLNS1A, UGP2, RNF216, PHGDH, CKAP4, and IL6R, many of which are known to participate in inflammatory pathways, oxidative stress, and endothelial dysfunction." (PMID 41262879, 2025).
glioblastoma (1 paper, 2025). The most malignant astrocytic tumor (WHO grade IV). "Conversely, UGP2 is aberrantly overexpressed in glioblastoma multiforme (GBM) and positively correlates with pathological grading, making it a potential biomarker for predicting GBM prognosis." (PMID 41614807, 2025).
intraepithelial neoplasia (1 paper, 2018). A precancerous neoplastic process that affects the squamous, glandular, or transitional cell epithelium without evidence of invasion. "In PT and BL with positive UGP2 and CFL1 expression, mild to severe atypical hyperplasia or intraepithelial neoplasia of grades II–III was observed in ductal epithelium." (PMID 29347944, 2018). "In paracancerous tissues and benign lesions with positive UGP2 and CFL1 expression, mild to severe atypical hyperplasia or grade II–III intraepithelial neoplasia was observed in the ductal epithelium." (PMID 29347944, 2018). "Additionally, the ductal epithelia of the paracancerous tissues and benign lesions with positive UGP2 and CFL1 expression showed mild to severe atypical hyperplasia or intraepithelial neoplasia (grades II–III)." (PMID 29347944, 2018).
lymph node metastasis (1 paper, 2018). "Kaplan-Meier survival analysis showed the degree of differentiation, tumor maximal diameter, TNM stage, lymph node metastasis, and surrounding invasion, and UGP2 and CFL1 expression were closely related to the average survival time of patients with PDC." (PMID 29347944, 2018).
nematodes infection (1 paper, 2021). "Metabolic pathways and biosynthesis of antibiotics may also be associated with T. gallinae infections probably due to the function of genes like UGP2 and OAT that were reported to play a role in nematodes infection and inhibiting Toxoplasma gondii." (PMID 34595226, 2021).
non-small cell lung carcinoma (1 paper, 2022). A group of at least three distinct histological types of lung cancer, including non-small cell squamous cell carcinoma, adenocarcinoma, and large cell carcinoma.
Portal vein thrombosis (1 paper, 2020). Thrombosis of the portal vein and/or its tributaries, which include the splenic vein and the superior and inferior mesenteric veins. "The univariate analysis showed that UGP2 expression, TNM stage, and portal vein thrombosis were significant prognostic factors for OS." (PMID 32733617, 2020).
tumor (20 papers, 2011 to 2025). "Additionally, lower UGP2 expression levels in patients with CRC were associated with more aggressive tumor behavior and poorer clinical outcomes, highlighting its potential as a prognostic marker." (PMID 41614807, 2025). "Bioinformatic analyses further linked UGP2 promoter hypermethylation to transcriptional silencing and favorable prognosis, and revealed a positive correlation between UGP2 expression and immune cell infiltration within the tumor microenvironment." (PMID 41614807, 2025). "UGP2 expression positively correlated with immune cell infiltration within the tumor microenvironment." (PMID 41614807, 2025). "To further validate the function of UGP2 as a tumor suppressor gene on CRC at the cellular level, we conducted in vitro functional assays." (PMID 41614807, 2025). "Collectively, these findings establish UGP2 as a key CRC tumor suppressor whose downregulation drives malignant progression and predicts adverse clinical outcomes, suggesting its potential as a dual-purpose diagnostic and prognostic biomarker." (PMID 41614807, 2025). "Among the five types of purified polysaccharides, UGP1 and UGP2 have a strong inhibitory effect on the proliferation of tumor cells." (PMID 37175266, 2023). "According to the data acquired from the GTEx and TCGA, UGP2 expression was compared between normal and tumor samples." (PMID 35937991, 2022). "Previous studies have correlated low UGP2 expression in many tumour types with tumour progression and poor prognosis." (PMID 32733617, 2020). "The results showed that compared with normal tissues, UGP2 mRNA expression was significantly downregulated in most tumour types, including HCC (P < 0.001)." (PMID 32733617, 2020). "The observed decrease in these immune cell populations in the low UGP2 expression group may contribute to a less effective antitumor immune response, facilitating tumor growth and progression." (PMID 41614807, 2025). "This bioinformatic finding prompts the hypothesis that the tumor-suppressive effect of UGP2 downregulation in CRC may be partially mediated through a metabolic rewiring that impacts lipid metabolism." (PMID 41614807, 2025). "Our discovery that UGP2 acts as a tumor-suppressive factor in CRC indicates that its downregulation drives malignant progression and is associated with poor clinical outcomes, highlighting its potential as a dual-purpose diagnostic and prognostic candidate biomarker." (PMID 41614807, 2025). "This functional evidence reinforces the view that UGP2 is a tumor suppressor in CRC." (PMID 41614807, 2025). "We identified UGP2 as a significantly downregulated tumor-suppressive factor in CRC." (PMID 41614807, 2025). "Relative to tumor tissues, UGP2 expression was higher in normal samples." (PMID 35937991, 2022). "Consistent with the UGP2 mRNA expression observed in the TCGA dataset analysis, the pancancer TMA analysis also indicated that the protein expression level of UGP2 in most tumour tissues, including HCC, was lower than that in adjacent nontumour tissues (P < 0.001)." (PMID 32733617, 2020). "UDP-glucose pyrophosphorylase 2 (UGP2), the direct targets of YAP/TEADs complexes, regulates glycogen synthesis and protein N-glycosylation, whose deletion halters tumor growth." (PMID 40707469, 2025). "Cell types that are highly expressed in tumor tissues compared to normal tissues are CALM3+CD8+T cells-C1 and UGP2+Mac-C2 (p < 0.05)." (PMID 38361757, 2024). "The main chain of ginger polysaccharides HGP, EGP1, EGP2, UGP1 and UGP2 is →4)-α-d-Glc (1→ and -α-Manp-(1→, which has strong anti-tumor activity." (PMID 37175266, 2023). "Among the five types of tumor cells (H1975, Hela, HCT116, B16, and MCF-7), UGP1 and UGP2 have significantly different inhibitory effects on their proliferation." (PMID 37175266, 2023). "Ultimately, only two genes (UDP-glucose pyrophosphorylase 2 [UGP2], SDR39U1) were found to be significantly different from those in tumor and normal tissues." (PMID 35937991, 2022).
tumor (continued). "The translational upregulation of PGM1, UGP2 and GSK3A mediated by MYCT1 and RACK1 adjusted the flux of glycogen synthesis and glycogen shunt, which is crucial for modulating the tumor metabolic reprogramming." (PMID 35281731, 2022). "UGP2 plays an essential role in promoting HCC cell migration and tumor metastasis." (PMID 36006904, 2022). "The results indicated that the OS/PFS of HCC patients with lower UGP2 expression was shorter regardless of the tumour-node-metastasis (TNM) stage (P < 0.0001)." (PMID 32733617, 2020). "While UGP2 is widely recognized for its role in catalyzing the production of UDP-glucose for glycogen synthesis in normal physiology, our data strongly suggest a context-dependent, non-canonical tumor-suppressive role specifically within the tissue microenvironment of CRC." (PMID 41614807, 2025).
cancer (15 papers, 2011 to 2025). A tumor composed of atypical neoplastic, often pleomorphic cells that invade other tissues. "Although UGP2 has been implicated in tumorigenesis across multiple cancers, its precise role and clinical significance in CRC remain poorly understood." (PMID 41614807, 2025). "Uridine diphosphate-glucose pyrophosphorylase 2 (UGP2), a key enzyme in glycogen biosynthesis, has been reported to be associated with the occurrence and development of various cancer types." (PMID 32733617, 2020). "The consistent downregulation of UGP2 across the majority of cancer types underscores its importance in maintaining normal cellular functions and suggests a broader involvement in tumorigenesis and progression." (PMID 41614807, 2025). "A recent proteomics study showed that the UGP2 expression levels were significantly higher in some malignant tumors or malignant cells than in normal tissue or cells." (PMID 32028604, 2020). "UGP2 overexpression has also been demonstrated to promote cell migration and invasion, as well as enhanced glycogenesis in vitro, which provides UGP2 as a valuable target in cancer treatment." (PMID 32028604, 2020). "Recently, experimental proteomics methods showed that the UGP2 expression levels were significantly higher in some malignant tumors or malignant cells than in normal tissue or cells." (PMID 29347944, 2018). "These proteomics studies showed that the UGP2 expression level was significantly higher in cancer cells than in the corresponding normal cells or tissues." (PMID 29347944, 2018). "UGP2 contributes to cancer biology, including cell proliferation, apoptosis, and metastasis." (PMID 41614807, 2025). "It has also been reported that UDP-glucose pyrophosphorylase 2 (UGP2), an enzyme responsible for UDP-glucose biosynthesis, is up-regulated in several cancers and that this upregulation is also important for cancer cell survival, proliferation, and metastasis." (PMID 35413075, 2022). "This tissue-specific functional divergence underscores the complexity of cancer metabolism and positions UGP2 not just as a metabolic housekeeping gene but as a context-dependent metabolic regulator with opposing roles in different cancers." (PMID 41614807, 2025). "Indeed, both UGP2 and AGX1/UAP1 have been shown to play a role in cancer growth." (PMID 32028604, 2020).
infection (6 papers, 2016 to 2023). The state of being infected such as from the introduction of a foreign agent such as serum, vaccine, antigenic substance or organism. "To test the requirement for UDP-Glc for luminal glycogen synthesis we silenced the expression of the host UDP-Glc pyrophosphorylase UGP2 (UGP2 catalyzes the conversion of Glc1P into UDP-Glc) by siRNA for two days before infection." (PMID 26981769, 2016).
colon polyp (1 paper, 2025). "Specifically, UGP2 expression was significantly downregulated in CRC tissues compared with that in normal controls and exhibited strong correlations with aggressive clinicopathological features, including lymphatic invasion, perineural invasion, and colon polyp history, and patient age." (PMID 41614807, 2025).
UGP2 also shares sentences with these, for which no sentence is quoted: adenoma (3 papers); lung carcinoma (3); cyst (2); Epileptic encephalopathy (2); genetic disease (2); glioma (2); acute myeloid leukaemia (1); Barakat–Perenthaler syndrome (1); chronic pancreatitis (1); colon cancer (1); diabetes (1); diabetic retinopathy (1); gastric cancer (1); heart failure (1); hepatoblastoma (1); liver cirrhosis (1); liver diseases (1); male infertility (1); pulmonary hypertension (1); thrombosis (1).